CD9 (CD9 molecule)
Diseases named in the same sentence as CD9 in open-access papers (continued):
Sharing a sentence is not in itself a finding about the gene and the disease.
tumor (284 papers, 1999 to 2026). "The results revealed a significant increase in the abundance of neoplastic-stemness, neoplastic-CD9, microglia, and tumor-associated macrophages in tumor tissues compared to normal brain tissues, with the most pronounced increase in neoplastic-stemness." (PMID 40076844, 2025). "Fractions E2–E5 stained positively for the exosome-specific protein markers CD9 (27 kDa) and Tumour Susceptibility Gene 101 (TSG101; 44 kDa)." (PMID 40748658, 2025). "As CD9 has been implicated in both anti-tumor immunity and pro-tumor immunity, the effects of blocking CD9 in immune-competent mice requires further exploration prior to implementation into clinical trials." (PMID 37542044, 2023). "These analyses showed substantial enrichment of the multivesicular body marker TSG101 (tumor susceptibility 101) and cell surface marker CD9." (PMID 36612172, 2022). "In acute lymphoblastic leukemia, CD9 expression was associated with a poor prognosis as well as its overexpression in an aggressive tumor like esophageal squamous cell correlated with tumor clinical staging and lymph node involvement." (PMID 35563166, 2022). "Multicomparison studies also revealed that the expression of CD9 was associated with tumor size, whereas CD63 upregulation was associated with histological diagnosis and vascular invasion." (PMID 34065085, 2021). "Reports have demonstrated that CD9 is implicated in the motility, adhesion, and activation of cells and hence plays a pivotal role in tumour growth, sperm-egg fusion, virus susceptibility, and tumour metastasis." (PMID 33597018, 2021). "Our in vivo data demonstrated a decrease in primary tumour growth associated to a reduced proliferation that was more evident for CD9 peptide treatment, accompanied by a reduced tumour infiltration." (PMID 34012515, 2021). "A third example of a tumour-associated antigen expressed on haematologic as well as solid malignancies is CD9." (PMID 35754458, 2020). "This is an important consideration in terms of tumor function, as in addition to loss of CD9 expression, factors that act at the 3’UTR have great capacity to affect many proteins leading to widespread functional differences." (PMID 29416746, 2018). "Decreased expression of CD9 in several human tumours is associated with increased metastatic potential." (PMID 30566430, 2018). "CD9 encodes the transmembrane protein tetraspanin which is involved in tumor cell invasion, apoptosis and resistance to chemotherapy." (PMID 26573230, 2016). "Data obtained from primary tumors suggested that high-level CD9 expression is associated with favorable tumor biology." (PMID 27572323, 2016). "TSPANs like CD9 (the closest TSPAN2 relative) or CD151 are associated with many stages in tumor formation or increased metastasis in various cancers." (PMID 25814554, 2015). "Upon transplantation of CD9-deficient cells in a murine model, an inhibition of tumor growth was observed after one week as well as a partial loss of metastatic capacity." (PMID 25762645, 2015). "Loss of CD9 expression has been correlated with a higher motility and metastatic potential of tumour cells originating from different organs." (PMID 21206492, 2011). "This demonstrates the causal role of trogocytosed CD9 in dampening NK-cell anti-tumor responses." (PMID 41181711, 2025). "Indeed, we demonstrated that targeting this cluster through knocking down or inhibition the main DEG associated with the cluster CD9 markedly decreased tumor growth and sensitized cells to an array of targeted and chemotherapy agents." (PMID 37542044, 2023). "TReg cells are linked to tumor progression via their promotion of immune suppression, and we thus hypothesized that cMo_CD33hi and nMo_CD9+ monocytes would negatively correspond with TReg frequencies." (PMID 35493454, 2022). "Additionally, CD151 and CD9 are tightly associated with activities of tumor-initiating cells or CSCs." (PMID 33919420, 2021).
tumor (continued). "Both normal and tumour‐associated EVs were strongly positive for CD9, CD81 and CD63." (PMID 34596356, 2021). "On a molecular level, CD9 is known to inhibit integrin-mediated motility and associate with the platelet aggregation-inducting factor podoplanin, thereby preventing platelet aggregation and, consequently, a tumor-cell protective microenvironment." (PMID 27572323, 2016). "The CD9-deficient cells could initiate the growth of tumor until 7th day post-injection in agreement with in vitro data, however, the cancer progression was afterward stopped and in several cases a complete regression was observed." (PMID 25762645, 2015). "Nevertheless, an increasing number of studies have suggested that CD9 may be markedly associated with tumor endothelial cell (EC) interactions during transendothelial invasion." (PMID 24520284, 2014). "These tumor associated mesenchymal cells (TAMCs) were closely associated with tumor cells and shared some homology with bone marrow- and adipose- derived MSCs (CD9, CD10, CD29, CD146, CD166, HLA-1)." (PMID 25303976, 2014). "It is worth mentioning, however, that although the association of the loss of CD9 with the metastatic status of tumours is highly significant and in agreement with the literature, our appreciation of CD9 expression within the tumour core was certainly overestimated." (PMID 21206492, 2011). "Furthermore, loss of CD9 has been correlated with a higher motility and metastatic potential of the following tumour cells: lung, oral, oesophageal, ovarian, cervical, and gastric." (PMID 21206492, 2011). "However, there was a highly significant association between CD9 expression and tumour grade (P=0.0007)." (PMID 14735195, 2004). "Among all parameters analysed, such as tumour grade, location, age, lymph node status, UICC stage classification, tumour grade was the only parameter to show a significant association with CD9 expression: low grade tumours appeared to express the CD9 protein more frequently." (PMID 14735195, 2004). "Although our hypothesis certainly needs further experimental validation, supporting reports suggest that FASN-mediated changes in specific fatty acids can promote tumor cell migration, and CD9 overexpression is associated with cells transitioning to a metastatic state." (PMID 40163697, 2025). "Thus, tumor cell-released Hsp70 and Hsp90 were associated with CD9/TSG101/AchE-positive EVs." (PMID 28928431, 2017). "Since PaCa-EVs uptake rate was found to be higher than non-tumor EVs; hence, we evaluated CD9 and CD81 expression in our EVs preparations." (PMID 41545338, 2026). "By combining bioinformatics analysis with functional validation, we found that CD9 is significantly upregulated in ESCC and is associated with tumor staging and lymph node metastasis, suggesting its possible involvement in tumor progression." (PMID 40860827, 2025). "MCT1 + CD9 + EV levels were higher in preoperative than in postoperative blood samples, mirroring reduced tumour burden." (PMID 39797974, 2025). "Analysis of PD-1 and TIM-3 co-expression revealed a significant enrichment in the tumor for cNK cells and the CD9+CD103−CD49a− subset, a pattern also observed in total NK cells." (PMID 41268557, 2025). "In-vitro co-culture of NK-92 cell line with HGSC cells resulted in trogocytic transfer of CD9 from the tumor cells to NK cells." (PMID 41181711, 2025). "CD9 exhibits a double-edged sword effect in various types of tumors, serving as both a tumor suppressor and a promoter of cancer in tumor occurrence/metastasis." (PMID 40860827, 2025). "Alterations in the expression, localization, and vesicular secretion of CD9 have been identified in a variety of neoplasms." (PMID 40565320, 2025). "Single-cell analysis revealed CD9-driven NPC-to-OPC transdifferentiation, linked to tumor proliferation." (PMID 40406701, 2025).
tumor (continued). "This system effectively reverses tumor-induced immunosuppression by targeting the PD-L1/CD9 dual pathway, thereby inhibiting tumor exosome-mediated migration." (PMID 41322140, 2025). "CD9 on matrix immune cells is related to longer disease-free survival, while CD9 on tumor cells is related to lymph nodes and distant metastasis." (PMID 40860827, 2025). "This acquisition of CD9 hampered the cytotoxic activity of NK cells with reduced production of anti-tumor cytokines." (PMID 41181711, 2025). "CD9, a transmembrane protein, has been reported to regulate tumor cell proliferation, apoptosis, migration, and invasion in various cancers." (PMID 40406701, 2025). "Recent studies have reported the emergence in cancer patients of both circulating and tumor-infiltrating NK cells expressing at least one of the CD9, CD49a, and CD103 markers." (PMID 40610398, 2025). "In paired analysis, glioblastomapatients exhibited a 3.9-folddecrease of TNC+/CD9+ EVs after tumor removal(p < 0.001)." (PMID 40056466, 2025). "Previous studies have demonstrated that the core genes of NPC-RSS, including SMARCA2, DMC1, CD9, PSG4, and KNG1, are associated with tumor radiosensitization to varying degrees." (PMID 40530955, 2025). "t-SNE projections revealed a striking enrichment of CD103, CD49a, and CD9 expression in TINKs compared to LINKs, suggesting distinct phenotypic reprogramming within the tumor milieu." (PMID 41268557, 2025). "It has shown that CD9 plays a crucial role in biological behaviors such as cell proliferation, migration, and apoptosis, particularly in the metastasis and invasion of tumor cells." (PMID 40860827, 2025). "In vitro experiments further confirmed that tumor-cell-co-cultured NK cells exhibited a decidual-like status, as evidenced by remarkable increasing CD9 expression." (PMID 39387546, 2024). "In recent years, considerable studies have shown that CD9 plays a pro-tumor and anti-tumor role in cancer development." (PMID 38389703, 2024). "This approach is based on the fact that infiltrated NK cells within the tumor make contact, via CD9 and CD103, with αv integrin on GSCs; this cell contact mediates the release of TGF-β1 by GSCs, which in turn suppresses the cytotoxic function of NK cells." (PMID 38256140, 2024). "CD63 and CD9 tetraspanins promote tumor development and determine invasiveness in certain cancer types, while glycosylation, as a post-translational process, has a key role in modulating the expression and molecular function of these membrane proteins." (PMID 39766023, 2024). "In order to ascertain the role of CD9 in JQ1 resistance in a tumor model, we determined the effect of CD9 knockdown and blockade with an anti-CD9 antibody on response to JQ1 in SUM149 xenografts." (PMID 37542044, 2023). "For instance, CD9(+) EVs in cancer have been shown to support tumor progression, invasion, and metastasis by transferring oncogenic proteins and miRNAs to recipient cells." (PMID 37371093, 2023). "Nevertheless, the CD9 protein plays a dual role in cancer progression, exhibiting both tumor-supportive and tumor-suppressive properties that are context-dependent." (PMID 37007105, 2023). "Both knockdown of CD9 and CD9 antibody treatment combined with JQ1 resulted in improved tumor control and also a marked increase in response to a suite of targeted and chemotherapy agents." (PMID 37542044, 2023). "Bioactive molecules, including CD9 in exosomes derived from cancer and stromal cells, provide the essential signals for the re-education of various cells and remodeling the tumor architecture." (PMID 37007105, 2023). "Consistent with the effects of CD9 knockdown, anti-CD9 treatment combined with low doses of JQ1 (1/5 of dose used in a previous study) markedly controlled tumor growth." (PMID 37542044, 2023). "For instance, a subset of PDAC tumor-initiating cells expresses high cell surface levels of stem marker CD9." (PMID 36768660, 2023).
tumor (continued). "Expression of the well-accepted exosome marker proteins, CD9, CD63, and Tumor Susceptibility Gene 101 (TSG101), were identified by western blot." (PMID 36697384, 2023). "CD9 and CD63 have been reported to associate with the metastatic ability of tumor cells, such that higher expression promotes decreased cell motility." (PMID 37355988, 2023). "CD9 trogocytosis from tumor cells onto NK cells were shown to promote reactivation of A disintegrin and metalloprotease (ADAM) 10 and 17 which both participate in the shedding of NK ligands and NK receptors." (PMID 37974170, 2023). "In PDAC tumor-initiating cells, CD9 interacts with the glutamine transporter ASCT2 and promotes its plasma membrane localization, thereby directly enhancing glutamine uptake and replenishment of the TCA cycle." (PMID 36768660, 2023). "The CD9 upregulation associated with enhanced expression of TNF-alpha and NFkB signaling and treatment with CD9 blocking antibody ALB6 resulted in reduced tumor growth in-vivo." (PMID 37007105, 2023). "Specifically, we demonstrated that plasma membrane protrusions and EVs left behind by tumor cells during migration are strongly positive for CD9." (PMID 35574334, 2022). "The tool is demonstrated by detection of EVs isolated from cell culture supernatants and various body fluids using characteristic biomarkers, CD9 and CD81, and a tumor-associated marker—epithelial cell adhesion molecules." (PMID 35564289, 2022). "In PDAC, CD9-positive cells have tumor-initiating capacity and give rise to tumor heterogeneity with high levels of expression being strongly associated with poor prognosis." (PMID 36009530, 2022). "At multivariate analysis with Cox proportional hazard model, tumor ulceration, CD9 expression, and SNB status resulted in independent prognostic factors associated with MSS." (PMID 35563166, 2022). "The authors found that the tumor sites with high localized CD9 positivity showed cones expanding into lymphatic or blood vessels and suggested a tetraspanin functional role in transendothelial migration as a critical step in lymph node metastases development." (PMID 35563166, 2022). "Meanwhile, bioinformatics analysis of data from UALCAN showed that the high expression of five genes (except CD9) was related to an advanced tumour grade." (PMID 36282889, 2022). "CD9 is a protein of the tetraspanin family, involved in both physiological and pathological events such as tumor progression and metastasis." (PMID 35955786, 2022). "It is now recognized that prognostic and clinicopathological significance of CD9 expression is controversial and changed with respect to the tumor type." (PMID 35563166, 2022). "Immunostaining was performed to assess both proliferative/stem cell (Nestin, Sox2, Ki67, Vimentin, SSEA1, CD133) and quiescent (Cd9 and Gfap) markers within the tumours." (PMID 36420140, 2022). "This is also supported by our other important finding, namely that CD9 was associated with significantly increased risk for SNB positivity, as well as tumor ulceration and Breslow thickness." (PMID 35563166, 2022). "Following the ISEV2018 guidelines, the EV characterization showed the presence of the EV-specific markers: CD9 molecule (CD9), CD81 molecule (CD81), and Tumor Susceptibility 101 (TSG101) in our serum." (PMID 35659238, 2022). "CD9, CD63, or glypican-1 can be taken into consideration as generic tumor-associated markers of exosomes produced by a major group of cancers." (PMID 35757760, 2022). "We successfully tested the tool for quantification of EVs harboring common EV markers, namely, CD9 and CD81, and a tumor-associated biomarker EpCAM." (PMID 35564289, 2022). "Increased expression of CD9 and CD81 was detected in multiple tumors and associated with increased tumor cell motility and improved tumor growth." (PMID 36203458, 2022).
tumor (continued). "Here, a nanotechnology approach is reported for tumor homologous targeting via CD9 and phagocytosis escape via CD47 through UE−coated poly (2−ethyl−2−oxazoline)−poly (D, L−lactide) (PEOz−PLA) nanoparticles (UEPP NPs)." (PMID 36004889, 2022). "The circulating level of MCT1+CD9+ EVs in the serum reflected tumor burden in both SS-bearing mice and patients." (PMID 33920416, 2021). "The reduction in size in both primary tumours and metastases suggest an impairment of tumour cell growth, which was confirmed by Ki67 staining in histological sections from tumours treated with CD9 peptide and in a lesser extent with CD63 peptide." (PMID 34012515, 2021). "Our analyses revealed that the overall relative expression (mean ± SD) of CD9 was significantly down-regulated by nearly 50% in tumor samples compared to normal tissues (p = 0.0006)." (PMID 34065085, 2021). "Collectively, serum MCT1+CD9+ EVs accurately reflected the tumor burden, indicating their potential for clinical use for tumor monitoring in patients with SS." (PMID 33920416, 2021). "The CD9 downregulation has been correlated with tumor progression, and is often found in late-stage tumors." (PMID 33669943, 2021). "Serum MCT1+CD9+ EVs slightly decreased after neoadjuvant chemotherapy and further decreased after tumor resection." (PMID 33920416, 2021). "Some studies have reported that CSCs can contribute towards tumor formation by upregulating CD9, thereby maintaining the tumor cell population." (PMID 33588867, 2021). "In the TME, CD9 suppresses motility and promotes adherence to the surrounding matrix which subsequently leads to a suppression of tumor progression." (PMID 33669943, 2021). "CD9 has been reported to behave either as a tumour suppressor or promoter depending on the tumour studied (as most recent examples see)." (PMID 34012515, 2021). "Cells with high CD9 expression have increased organoid formation capability and generate tumor grafts more easily in vivo." (PMID 33912458, 2021). "In spite of the small sample size, we found that the circulating MCT1+CD9+ EVs in the serum reflected the tumor burden or treatment response in vivo, indicating the potential for the translation of this liquid biopsy into clinics for the management of SS." (PMID 33920416, 2021). "CD9, CD63, and CD81, in conjunction with other tetraspanins, promote (in association with exosomes) cancer cell motility, invasion, metastasis, tumor initiation, promotion, progression, and angiogenesis." (PMID 33669943, 2021). "The tumor pre-NCCR rectal biopsy mean CD9 score was 130 in patients with low-intermediate NAR scores compared to 144 in patients with high NAR scores (P = 0.5519)." (PMID 34316329, 2021). "We next analyzed the serum MCT1+CD9+ EV levels in the collected blood samples just after tumor resection." (PMID 33920416, 2021). "MCT1+CD9+ EVs were also detected from SS-bearing mice and their expression levels were significantly correlated with tumor volume (p = 0.003)." (PMID 33920416, 2021). "The major effect observed upon treatment with CD9 peptide in vivo was a reduction in tumour cell proliferation." (PMID 34012515, 2021). "Tumor-bearing mice increased exosomal protein content in blood circulation and exosomal cargo proteins CD9 and HSP70." (PMID 33669632, 2021). "Circulating levels of MCT1+CD9+ EVs were significantly correlated with tumor volume in a SS mouse model." (PMID 33920416, 2021). "The C649T, C1467G and T488C + G791A + G2153A mutations are loss-of-function mutations, which inhibit the transport of extracellular matrix proteins, such as EPCAM and CD9, thereby attenuating cell adhesion and promoting tumor metastasis." (PMID 32123160, 2020).